CXCR3 (C-X-C motif chemokine receptor 3)
Diseases named in the same sentence as CXCR3 in open-access papers (continued):
Sharing a sentence is not in itself a finding about the gene and the disease.
tumor (continued). "Our study defines LRP1 as a regulator of CXCR3, which may have important consequences for tumor biology." (PMID 29146996, 2017). "The expression of CXCR3 in tumor cells was scored semiquantiatively as 0, 1+, 2+ or 3+." (PMID 28504691, 2017). "Our data are consistent with chemoattraction of circulating CXCR3+ monocytes to lungs following injection of tumor cells, which may induce the production of chemokines." (PMID 28358049, 2017). "Elevated serum CXCL10 and increased expression of CXCL10 and CXCR3 in tumor cells have been associated with a poor prognosis and metastasis (50, 51, 56, –, 58), suggesting that the CXCL10–CXCR3 axis may promote CRC progression in some cases." (PMID 28717003, 2017). "CXCR3 is express in various cell types including endothelial cells, immune cells or tumor cells." (PMID 28878333, 2017). "Other than in relation to metastasis, inhibition of CXCR3 was also known to mediate tumor growth." (PMID 28841719, 2017). "Although the chemokine CXCL10 is known to exert anti-angiogenic properties and mediate the recruitment of CXCR3-expressing mononuclear cells with anti-tumor activities, CXCL10 and its receptor CXCR3 are increasingly being recognized as pro-tumorigenic in several types of cancers, including CRC." (PMID 28717003, 2017). "Still, the double-edged role of CXCR3 jeopardizes any CXCR3-targeted therapy apporach; targeting tumor cell CXCR3 in cancer patients may simultaneously limit the CXCR3-mediated lymphocytic tumor infiltration." (PMID 28504691, 2017). "In primary tumors, CXCR3 was particularly overexpressed by tumor cells at the invasive front." (PMID 28504691, 2017). "In addition, molecular approaches aimed at improving host immune environment and simultaneously targeting tumor cells such as CXCR3 should be more effective." (PMID 27223426, 2017). "The presence of specific chemokines in the tumor microenvironment, including ligands for the chemokine receptors CXCR3 and CX3CR1, has been shown to promote intratumoral infiltration of T and NK cells and correlate with increased survival in a variety of cancers." (PMID 28923105, 2017). "In addition, overexpression of CXCR3 at the invasive tumor front and its upregulation in intraabdominal metastases suggest a role for CXCR3 in the selection of tumor cells into peritoneal metastatic niches." (PMID 28504691, 2017). "Thus, the relative expression between the two CXCR3 isoforms in tumor cells determines the behavior of cells in response to agonist stimulation." (PMID 28878333, 2017). "CXCR3 was high on spleen T cells and low on tumor T cells independently of the injected treatment." (PMID 28986561, 2017). "Indeed, blocking their common receptor CXCR3 in vivo prevented the therapeutic effects, possibly due to counteracting trafficking of effector T cells across tumor vessels." (PMID 28123870, 2016). "Indeed, tumor growth reduction achieved by combination treatment was significantly hampered by CXCR3 blockade (p < 0.05) and tumor weight distributions clearly visualized the high numbers of large tumors (>1.0 g) and complete absence of small tumors (<0.5 g)." (PMID 28123870, 2016). "Here we report that CXCR3 KD in tumor cells inhibited tumor cell migration and metastasis." (PMID 26485767, 2015). "To examine whether the tumor microenvironment has an effect on CXCR3 expression, we next examined CXCR3 expression level in tumor cells from primary tumor tissues compared to those in culture." (PMID 26485767, 2015). "Furthermore, the majority of Ki67+ proliferating Tregs in the tumor co-expressed CXCR3, as was true for intra-tumoral Tconvs." (PMID 26433463, 2015). "CXCR3 has been reported to play a role in tumor progression and metastasis in a number of cancers." (PMID 26485767, 2015). "Indeed, individual inhibitors of CXCR4, CXCR7 (CCX2066, ChemoCentryx), and CXCR3 (AMG487) showed partial effectiveness in reducing tumour growth and metastasis and they are still in preclinical studies." (PMID 26062132, 2015).
tumor (continued). "However, in disagreement with these publications, and our data, CXCR3-dependent anti-tumor response has also been reported." (PMID 26485767, 2015). "Interestingly, tumor infiltrating CD56bright NK cells express high levels of two of these dNK markers: CXCR3 and CD9." (PMID 26079948, 2015). "In contrast, most labelled CD4+ T cells recovered from the tumour were from CXCR3−/− animals." (PMID 25495686, 2015). "Thus, the demonstration that T-bet+ CXCR3-expressing Tregs accumulate in human ovarian cancer has lent support to the theory that Tregs must ‘mirror’ the TH1-orientated anti-tumor response in order to effect immunosuppression." (PMID 26433463, 2015). "Knockdown (KD) of CXCR3 in metastatic tumor cells suppressed tumor cell migration and metastasis." (PMID 26485767, 2015). "Moreover, a significantly higher frequency of CD4+ T cells expressing CXCR3 was found in the tumours compared with NDLN." (PMID 25495686, 2015). "Our study, using both genetic and chemical approaches, demonstrates that CXCR3 inhibition could inhibit tumor cell metastatic capability and, at the same time, improve host anti-tumor immunity." (PMID 26485767, 2015). "CXCR3 is uniquely up-regulated on Tc1, which is critical for efficient CNS tumor-homing of Tc1." (PMID 26528477, 2015). "To determine whether CXCR3 was required for intra-tumoural recruitment of CD4+ T cells we tested whether CXCR3-desensitization through pre-incubation with CXCL10 would interfere with the ability of adoptively transferred T cells to access the tumour." (PMID 25495686, 2015). "Similarly, the frequency of CXCR3 was significantly higher on tumor-infiltrating CD8+ T lymphocytes than their circulating counterparts (44.52 ± 23.44% vs. 11.62 ± 9.86%, p < 0.0001)." (PMID 26317795, 2015). "Here we evaluate the effect of CXCR3 targeting on both the tumor cells and the host compartments." (PMID 26485767, 2015). "Further studies showed that the full potency of CCL21-mediated anti-tumor response required the induction of IFN-γ, MIG/CXCL9 and IP-10/CXCL10 in concert, as neutralization or depletion of any one of these cytokines led to a decrease in the frequency of CXCR3+ve T cells and CD11c+ve DC in the tumor." (PMID 24810425, 2014). "Accumulating data implicate CXCR3 signaling in promotion of tumor growth, migration and invasion." (PMID 25415223, 2014). "Likewise, in a murine cutaneous tumour model, the recruitment of CXCR3-bearing effector cells by CXCL9 correlated positively with tumour rejection." (PMID 24961933, 2014). "In addition, we found that CXCR3 mRNA was expressed in the cells surrounding the tumor, and that Mig and IP-10, the ligand of CXCR3, was expressed in the tumor lesion itself." (PMID 25123545, 2014). "CXCL11 binds to its cognate receptor CXCR3 overexpressed by the tumor cells, which could promote cell proliferation and migration." (PMID 24384839, 2013). "CXCL10, at the same time, attracts CXCR3-expressing Th1 cells to the tumor site." (PMID 22408433, 2012). "Finally, the chemokine receptor CCR5, which is usually co-expressed with CXCR3 on Th1 cells was expressed in similar frequencies in tumor and unaffected mucosa." (PMID 22319577, 2012). "Above median expression of CXCR2, CXCR3 and CCR1 in the tumour islets is associated with increased survival in NSCLC, and expression of CXCR3 correlates with increased macrophage and mast cell infiltration in the tumour islets." (PMID 20429924, 2010). "As CXCR3 antagonism may not only impact on tumour cells but also on CXCR3-dependent immune mechanisms as well, working with the immunocompetent metastatic models appeared more appropriate to assess the anti-metastatic potential of this strategy." (PMID 19436305, 2009). "Despite accumulating evidence of malignancy-related functions of CXCR3 in various cancers, the functions that chemokines and their receptors establish between the tumour cells and their microenvironment are complex, ranging from support to inhibition of the tumourigenesis process." (PMID 19436305, 2009).
tumor (continued). "On the basis of the chemotactic effect of CXCR3 ligands on the CRC tumour cells in vitro, we further tested the hypothesis that metastases implantation in the liver and in the lung is facilitated by CXCR3 expression on the tumour cell surface." (PMID 19436305, 2009). "To differentiate between CXCR3 expression by the tumour tissues and that by the surrounding healthy organ, we have examined the human HT29 metastases implanted within mouse tissues using antibodies specifically directed against the human protein through immunohistochemistry." (PMID 19436305, 2009). "Interestingly, the curative systemic antagonism of CXCR3 markedly reduced both the number of nodules and the cumulative tumour volume within lungs of both HT29 and C26-inoculated mice whereas liver tumours remained unaffected." (PMID 19436305, 2009). "Both CXCL9/MIG and CXCL10/IP-10 are chemotactic for stimulated CXCR3-expressing T lymphocytes that could further amplify IFN-γ at the tumour site." (PMID 16598185, 2006). "Astaxanthin was associated with a higher quantity of tumor‐associated macrophages, infiltration of CD8+ T cells, Tumor Granzyme B, IL‐2, serum TNF‐α and interferon‐γ, genetic transcription of CXCL9, CXCL10, and CXCR3, and mRNA expression of cluster of differentiation." (PMID 40071130, 2025). "CXC chemokine receptor 3 (CXCR3) is a G protein-coupled chemokine receptor that plays a key role in regulating immune responses and is involved in various pathological processes, particularly in tumor development and inflammatory diseases, making it a novel target for clinical therapy." (PMID 40786052, 2025). "Conversely, some studies suggest that concomitant active TB in SCC may paradoxically improve survival through enhanced T-cell mediated anti-tumor immunity, with increased CD3+ T cells, CXCR3+ cells and decreased regulatory T cells in the tumor microenvironment." (PMID 41322988, 2025). "Specifically, the use of photoconvertible immune cell reporters (e.g., Kaede or KikGR mice) and longitudinal in vivo imaging could be employed to definitively demonstrate the sequestration of CXCR3+ effector cells in the lungs or circulation in response to tumor-driven CXCL10 gradients." (PMID 41516196, 2025). "Importantly, the observed TME remodeling was not merely a bystander effect but a direct consequence of CAR-M’s ability to simultaneously eliminate tumor cells and secrete chemotactic signals like Cxcl10, which recruits CXCR3+ T cells to establish an inflamed microenvironment." (PMID 41388305, 2025). "Moreover, they suggest the TLR3/TICAM-1 may contribute to previously reported CXCL10-mediated recruitment of CXCR3-positive lymphocytes to the tumor microenvironment." (PMID 40029556, 2025). "Lower granzyme B, at least by some NK cell subsets, besides higher CXCR3 expression per total NK cells collectively suggest that NK cells in BC have a potency to be recruited to the tumor site, but these cells, or at least some of their subsets, may not be able to render their cytotoxic effects." (PMID 38652012, 2024). "Hence, CXCR3’s role in tumor immunology warrants further investigation." (PMID 39596815, 2024). "Moreover, activators of FAO, like bezafibrate, could potentiate anti-PD-1 therapy by inducing the expression of CXCL9 and CXCL10 from tumor cells and CXCR3 on intra-tumor effector T cells." (PMID 39119332, 2024). "However, IP-10 may also partake in tumor expansion if the receptor CXCR3 is overexpressed in cancer cells." (PMID 38504975, 2024). "High CXCR3 expression on activated T cells has not only been shown to be a robust predictor for the success of cell-based immunotherapies but may also be upregulated in tumor-resident T cells due to immune checkpoint inhibition-induced T cell activation." (PMID 39196448, 2024).
tumor (continued). "Therefore, this study hypothesized that the increase in CXCR3+ T cells in the blood of treatment-resistant patients might be caused by a decrease in the activation of CXCL9 and CXCL10 inside the tumor microenvironment." (PMID 39273452, 2024). "In addition, through boosting cell migration and invasion, CXCR3B downregulation may switch PCa tumor metastasis from “stop” to “go” modifying CXCR3 isoform expression influences PCa cell migration and invasion." (PMID 38745115, 2024). "Interestingly though, the upregulation of CXCR3 on anti‐tumor T cells within the tumor microenvironment may be even more important than its role outside the tumor." (PMID 38922759, 2024). "In addition, the recruitment of cDC1 within tumors has other benefits, including the production of chemokines CXCL9 and CXCL10 to recruit CXCR3 effector T cells for tumor infiltration, and a further enhancement of the antitumor activity of T cells and NKs by cytokine IL-12." (PMID 38339158, 2024). "The study also found that oral supplementation of Akkermansia muciniphila could restore the efficacy of PD-1 blockade after antibiotic treatment, an effect that depends on IL-12 and is mediated by increasing the infiltration of CCR9+CXCR3+CD4+ T lymphocytes into the tumor bed of mice." (PMID 39885985, 2024). "Taken together, these in silico and in vitro analyses suggest that the CXCR3 chemokine axis may play an important role in tumor progression related to inhibition of anti-tumor immunity, but whether this role could be exploited to impede tumor growth was previously untested." (PMID 37686653, 2023). "In addition, CXCR3 is a double-edged sword in tumor progression." (PMID 36690649, 2023). "Network analysis identified GPCR networks, specifically the CXCR3 chemokine axis, as modulators of tumor–immune interactions that may have proliferative effects on primary tumors, as well as a role for immunosurveillance, and may present opportunities for targeted therapy." (PMID 37686653, 2023). "To test whether the chemokine receptor CXCR3, expressed on the CD431B11+T cell subset and known to mediate adhesion induction, was also implicated in tumor migration, we blocked this chemokine receptor by antibodies provided during PDOX treatment of tumor-challenged mice." (PMID 36796366, 2023). "Furthermore, CXCL10 induces chemotaxis of CXCR3+ NK cells, resulting in tumor regression." (PMID 38035101, 2023). "Therefore, the CXCL10/CXCR3 axis was indispensable in RFA-triggered anti-tumor immunity." (PMID 36900218, 2023). "In vivo models demonstrated decreased tumor growth with antagonism of the CXCR3 receptor in immunodeficient but not immunocompetent mice, suggesting that the CXCR3 axis can drive tumor proliferation in an autocrine fashion, but the effect is tempered by an intact immune system." (PMID 37686653, 2023). "In addition, a co-expression pattern was identified for PF4/CXCR3 between ductal cells and T cells in PT tissues, suggesting a potential mechanism by which CXCR3+ T cells could be recruited to the tumor epithelium." (PMID 37612267, 2023). "However, there was a significant higher expression of CXCR3 with higher tumor stage (pT3/T4) and higher tumor grade (G3/G4), being in line with literature to date reporting that overexpression of IFN-inducible CXCR3 ligands predicted poorer oncological outcomes in the past." (PMID 36831346, 2023). "CXCR3 has two subtypes, CXCR3-A which induces chemotaxis and proliferation, favoring tumor growth and progression and CXCR3-B, inhibiting migration and inducing apoptosis, which may enhance anti-tumor immunity." (PMID 36831346, 2023). "Among 28 chemokine genes available, CXCL9/10/11/CXCR3, CXCL13/CXCR5 and XCL1/XCR1 mRNA expression were significantly increased in RCC compared to normal kidney tissue and also strongly associated with tumor-infiltrating effector memory and central memory CD8+ T cells in all investigated collectives." (PMID 37006314, 2023).
tumor (continued). "Therefore, we proposed a scientific hypothesis that thermal ablation treatment could induce TAM1 to express CXCL10, leading to the recruitment of CXCR3+CD8+T cells into the tumor site and enhancement of anti-tumor immunity." (PMID 36900218, 2023). "However, because CXCL10 is secreted from monocytes/macrophages and CXCR3 is expressed in lymphocytes, the selective inhibition of a signal pathway of tumor cells in immunocompetent transgenic mice is difficult, especially when immune cells and tumor cells share a common signal pathway." (PMID 36612121, 2022). "Therefore, radiation and TGFβ inhibition may synergize by enhancing T cell trafficking into the tumor through upregulation of both CXCR3 and its ligands." (PMID 36382146, 2022). "Unlike the PD-1/PD-L1 pathway, which plays a central role in regulating T cell exhaustion, the CXCR3 axis can promote the growth of effector T cells and killing of tumor cells, which implies that the CXCR3 axis may impact the effectiveness of tumor immunotherapy." (PMID 35562800, 2022). "However, either mechanism enhance the response of CXCR3 for anti-tumor immune response." (PMID 36479091, 2022). "However, the expression of chemokine receptor CXCR3, expressed on tumor-infiltrating cytotoxic T-cells, was not linked to inflammation." (PMID 35027623, 2022). "In the current study, we found that the expressions of CXCL9 and CXCR3 mRNA increased significantly in the lungs of Abt-Kras mice compared to paired controls as tumour progressed, and this may be the main reason for the constant amount of NK cells and CD8+T cells in their lung." (PMID 36033391, 2022). "Although we have not looked at an absolute requirement for CCL5 expression in the control of SCC in the present study, it is interesting to speculate that CCL5 may also be responsible for the small but detectible numbers of CD8 T cells present within the tumours of anti-CXCR3-treated mice." (PMID 33925140, 2021). "However, CD27+ (antiinflammation) and CXCR3+ (tumor trafficking) NK cells were decreased in ALS." (PMID 33974561, 2021). "Selective recruitment of CXCR3 (+) B cells Bridges the pro-inflammatory interleukin-17 response and the polarization of tumorigenic macrophages in the tumor environment, and blocking the migration or function of CXCR3 (+) B cells may contribute to the defeat of HCC." (PMID 34869376, 2021). "Therefore, IL-18 and IP-10/CXCL10 in NPC may play dual roles in the recruitment and suppression of CXCR3+ tumor infiltrating NK cells and T cells." (PMID 33718235, 2021). "Furthermore, whilst active paclitaxel therapy temporarily inhibited CXCR3-mediated CD8+ T cell migration to tumour tissue, the effect was transient and could be reversed." (PMID 33513866, 2021). "Hence, CXCR3 has a dual role as an oncogenic factor and tumor suppressor." (PMID 33407095, 2021). "Our results demonstrated that the elevated levels of CCL5 and CXCL10 produced by the irradiated tumors might attract the vaccinated CD8+ T cells with a high expression of IFN-γ+CXCR3+ into the tumor, resulting in an increased ratio of CD8+ T cells/Tregs in the tumor milieu." (PMID 33469123, 2021). "Furthermore, IFNγ, produced by activated CTLs and abundant in inflamed tumours, can induce CXCL9 and CXCL10 secretion in various intermediary cells, including tumour-infiltrating myeloid cells, which may enhance the role of CXCR3 in homing." (PMID 33046212, 2020). "A recent review reports that the CXCL9/CXCL10/CXCL11/CXCR3 axis is responsible for angiogenesis inhibition, and the activation and migration of immune cells such as cytotoxic lymphocytes and natural killer cells into the tumor microenvironment, to prevent tumor progression in BCa." (PMID 33003392, 2020). "CXCR3, an oncogene previously established as a prognostic marker for solid tumors, is a chemokine receptor involved in leukocyte trafficking and migration in response to chemotactic signals leading to tumor immunity and the promotion of cell migration and invasion." (PMID 32051475, 2020).